RNU6-116P (RNA, U6 small nuclear 116, pseudogene)
Gene: Small nuclear RNA gene on chromosome 18 (61,391,595 to 61,391,703, forward strand). Ensembl gene ENSG00000206769.
Homologues: Orthologues: chimpanzee U6 (100% identical), macaque U6 (96% identical), mouse Gm23648 (95% identical), mouse Gm26177 (93% identical), pig U6 (87% identical), rat U6 (86% identical), pig U6 (85% identical), rat U6 (83% identical). Paralogues in human: RNU6-33P (95% identical), RNU6-1 (94% identical), RNU6-1060P (94% identical), RNU6-15P (94% identical), RNU6-2 (94% identical), RNU6-3P (94% identical), RNU6-4P (94% identical), RNU6-5P (94% identical), RNU6-6P (94% identical), RNU6-9 (94% identical), RNU6-10P (94% identical), RNU6-12P (94% identical), and 1290 more.